SNORD115-3 (small nucleolar RNA, C/D box 115-3)
Synonyms: HBII-52-3
Gene: Small nucleolar RNA gene on chromosome 15 (25,174,927 to 25,175,008, forward strand). Ensembl gene ENSG00000199970.
Gene Ontology:
Biological process: RNA processing
Cellular component: nucleolus
Homologues: Orthologues: chimpanzee SNORD115 (100% identical), macaque SNORD115 (95% identical), dog SNORD115 (63% identical). Paralogues in human: SNORD115-11 (96% identical), SNORD115-29 (96% identical), SNORD115-36 (96% identical), SNORD115-43 (96% identical), SNORD115-12 (95% identical), SNORD115-16 (95% identical), SNORD115-22 (95% identical), SNORD115-26 (95% identical), SNORD115-39 (95% identical), SNORD115-44 (95% identical), SNORD115-6 (95% identical), SNORD115-9 (95% identical), and 37 more.